PRKCQ (protein kinase C theta)
Diseases named in the same sentence as PRKCQ in open-access papers (continued):
Sharing a sentence is not in itself a finding about the gene and the disease.
lymphoma (2 papers, 2021 to 2024). A malignant (clonal) proliferation of B- lymphocytes or T- lymphocytes which involves the lymph nodes, bone marrow and/or extranodal sites. "Analytical results indicated that some inferred genes, such as RAC3, TEC, IRAK2/3/4, PRKCE, SMAD3, BLK, TXK, PRKCQ, were associated with the initiation and progression of lymphoma." (PMID 34899868, 2021). "The analytical results showed that some of these genes (RAC3, TEC, IRAK2/3/4, PRKCE, SMAD3, BLK, TXK, PRKCQ) could be novel lymphoma-associated genes." (PMID 34899868, 2021). "Other inferred genes, such as BLK (ENSP00000259089), TXK (ENSP00000264316), and PRKCQ (ENSP00000263125), have also been associated with lymphoma." (PMID 34899868, 2021).
Obesity (2 papers, 2016 to 2026). Accumulation of substantial excess body fat. "Growing evidence indicates that PRKCQ is notably associated with the improvement of obesity." (PMID 41596924, 2026). "While the exact role appears complex, this foundational observation supports the broader premise that PRKCQ is a key regulator involved in obesity pathogenesis." (PMID 41596924, 2026). "This genetic functional study provides direct in vivo evidence for the protective role of PRKCQ against obesity." (PMID 41596924, 2026).
psoriasis (2 papers, 2016 to 2019). An autoimmune condition characterized by red, well-delineated plaques with silvery scales that are usually on the extensor surfaces and scalp. "The SNPs rs4750316, rs11258747, and rs947474 in the PRKCQ gene, which encodes a protein kinase C isoform involved in NF-κB activation and T-helper cell subset differentiation, were selected as SNP candidates based on their associations with RA, T1DM, and psoriasis." (PMID 26784953, 2016).
rheumatoid arthritis (2 papers, 2016 to 2022). A chronic, systemic autoimmune disorder characterized by inflammation in the synovial membranes and articular surfaces. "The 440kB region between PFKFB3 and Protein Kinase C Theta (PRKCQ) has been reported in a meta-analysis to identify rheumatoid arthritis (RA) risk loci in European populations, and also has been shown to be associated with T1D." (PMID 27015091, 2016).
anaplastic astrocytoma (1 paper, 2021). "In detail, one patient collected tumor specimens in all stages of MT in the present cohort.PRKCQ,PPIF,NRP1,MEFV,GGT1,FAN1, andBTKmutations were found in both DA and anaplastic astrocytoma, whereas mutations ofTBC1D19,ESRRA,DIAPH2,COG6, andCBWD3occurred in HGA." (PMID 34430964, 2021).
atopic dermatitis (1 paper, 2025). "Quantitative analysis revealed that the expression of NMB, IL2RA, IL1RL1, and PRKCQ was markedly elevated in individuals with atopic dermatitis relative to healthy controls (p < 0.05 or p < 0.01), indicating their possible involvement in disease development." (PMID 41346997, 2025).
celiac disease (1 paper, 2016). An autoimmune genetic disorder with an unknown pattern of inheritance that primarily affects the digestive tract. "In a meta-analysis of Dutch and UK data sets, shared association with this PFKFB3/PRKCQ region was observed in both RA and celiac disease." (PMID 27015091, 2016).
central nervous system autoimmune disease (1 paper, 2016). "PRKCQ has been identified as a positive regulator in diverse cellular signaling pathways and diseases, such as T-cell activation and central nervous system autoimmune disease." (PMID 27661005, 2016).
cervical cancer (1 paper, 2025). A primary or metastatic malignant neoplasm involving the cervix. "Using genetic variants as instrumental variables, we identified key genes such as FUOM, H2BC21, LAMTOR4, and PRKCQ, which demonstrated direct effects on cervical cancer susceptibility." (PMID 40817807, 2025). "However, PRKCQ demonstrated a significant negative causal relationship (p < 0.05), indicating that higher expression levels of PRKCQ may reduce the risk of cervical cancer." (PMID 40817807, 2025). "Additionally, PRKCQ and H2BC21 were significantly overexpressed in HeLa cells, whereas LAMTOR4 showed a slight but statistically significant decrease (p < 0.01), suggesting differential roles for these genes in cervical cancer biology." (PMID 40817807, 2025).
diabetes (1 paper, 2023). "For the insulin hormone, MultiCens detected PRKCQ-AS1, a natural antisense lncRNA for the diabetes drug-target and insulin signaling regulator PRKCQ (Protein kinase C theta)." (PMID 37093889, 2023).
epilepsy (1 paper, 2022). A brain disorder characterized by episodes of abnormally increased neuronal discharge resulting in transient episodes of sensory or motor neurological dysfunction, or psychic dysfunction. "As detailed here, the activated CD8 T cells had the strongest positive correlation with PRKCQ and a negative correlation with JAK2, which indicates that expression levels of PRKCQ and JAK2 in epilepsy play an important role in activated CD8 T cell infiltration." (PMID 36138892, 2022).
immunodeficiencies (1 paper, 2019). "In our recent study, PRKCQ and other PKC-family members were identified as target genes of miR-34a10 suggesting that aberrant expression of miRNA-34a plays a role for T cells associated immunodeficiencies by interfering with the CD3E-ZAP70-PRKCQ axis." (PMID 30718475, 2019).
juvenile idiopathic arthritis (1 paper, 2025). Juvenile idiopathic arthritis (JIA) is the term used to describe a group of inflammatory articular disorders of unknown cause that begin before the age of 16 and last over 6 weeks. "Other loci, including STAT4, tnf receptor associated factor 1(TRAF1)/C5, Chr6q23, kinesin family member 5A (KIF5A), and protein kinase C theta (PRKCQ)are involved in juvenile idiopathic arthritis." (PMID 40236704, 2025).
leiomyosarcoma (1 paper, 2012). An uncommon, aggressive malignant smooth muscle neoplasm, usually occurring in post-menopausal women. "Protein kinase C theta, a downstream effector in the KIT signaling pathway, is used to discriminate between GISTs and leiomyosarcoma or other tumors which have similar histopathology to GISTs." (PMID 22540369, 2012).
lung adenocarcinoma (1 paper, 2022). A carcinoma that arises from the lung and is characterized by the presence of malignant glandular epithelial cells. "PRKCQ expression is also decreased in lung adenocarcinoma and renal cell carcinoma compared to controls." (PMID 36578501, 2022).
melanoma (1 paper, 2021). A malignant, usually aggressive tumor composed of atypical, neoplastic melanocytes. "According to our study, coexpression of CCR2, CFLAR, PRKCQ, and LINC00324 was associated with autophagy in melanoma." (PMID 34250091, 2021).
Noonan syndrome (1 paper, 2017). Noonan Syndrome (NS) is characterized by short stature, typical facial dysmorphism and congenital heart defects. "Four of the proteins are linked to various forms of the Noonan syndrome (CBL, MAP2K1, RAF1 and SOS), 5 to various types of tumors (MAPK1, PRKCQ, ABL1, GRAP2 and RAS) and one to an autoimmune disorder (RASGRP1)." (PMID 28448599, 2017).
pneumonia (1 paper, 2026). An acute, acute and chronic, or chronic inflammation focally or diffusely affecting the lung parenchyma, caused by an infection in one or both of the lungs (by bacteria, viruses, fungi, or mycoplasma.). "Our computational-experimental pipeline prioritizes four biomarkers (NAMPT, NFKBIA, SLC40A1, PRKCQ) that stratify pneumonia risk and predict targeted drugs for therapeutic repurposing." (PMID 41557688, 2026). "Transcriptional profiling confirmed marked dysregulation of all four model genes (NAMPT, NFKBIA, SLC40A1, PRKCQ) in pneumonia cases versus controls (p < 0.001)." (PMID 41557688, 2026).
schizophrenia (1 paper, 2012). A major psychotic disorder characterized by abnormalities in the perception or expression of reality. "Besides categories related to hematological function, the Tan schizophrenia module was also enriched for the Neurological Disease category (CCL5, PRKCQ, PTAFR, AKR1B1, CD247, IL10RA and KHSRP)." (PMID 22761806, 2012).
Sepsis (1 paper, 2023). Sepsis is defined as life-threatening organ dysfunction caused by a dysregulated host response to infection. "The results showed that IKBKB and PRKCQ were significantly downregulated in the sepsis group, while SH3GLB1 and WIPI1 were significantly upregulated." (PMID 37701780, 2023). "The four key genes that were identified to have both significant diagnostic and prognostic value in sepsis (IKBKB, PRKCQ, WIPI1, and SH3GLB1) were validated by RT-qPCR in whole blood samples obtained from sepsis patients and healthy controls." (PMID 37701780, 2023).
type 1 diabetes (1 paper, 2025). "PRKCQ, encoding a member of the protein kinase C (PKC) family, is associated with type 1 diabetes by a large GWAS evidence, which could control biological processes involving T-cell integration and CD28 signaling." (PMID 41393296, 2025).
cancer (17 papers, 2012 to 2024). A tumor composed of atypical neoplastic, often pleomorphic cells that invade other tissues. "Consistent with this, one study reported that PRKCQ expression was positively correlated with tumor infiltrating lymphocytes, in the majority of cancer types analyzed, and was associated with improved patient survival." (PMID 38752473, 2024). "The monoallelic loss was most prevalent in PRKCD, then PRKCH, PRKCZ, and PRKCQ across many cancer types compared to other genes." (PMID 35174160, 2021). "The monoallelic loss was most prevalent in PRKCD, PRKCH, PRKCZ, and PRKCQ across different cancer types." (PMID 35174160, 2021). "Besides, PRKCD, PRKCH, PRKCZ, and PRKCQ were associated with varying degrees of low-level CNGs along with different cancers." (PMID 35174160, 2021). "Variations in both PRKCB and PRKCQ play significant roles in certain cancers and are considered excellent predictive biomarkers for these diseases." (PMID 39238930, 2024). "PRKCQ affects different processes in cancers, including tumor cell proliferation, migration, and invasion." (PMID 36189312, 2022). "In contrast, PRKCB, PRKCH, and PRKCQ expressions were positively correlated with TLLs among most cancer types." (PMID 35174160, 2021). "Intriguingly, we have previously shown that this nuclear phosphorylated form of LSD1-s111p is mediated by protein kinase-C theta (PKC-θ) in cancer stem cells (CSCs)." (PMID 31249575, 2019). "By studying the relationship between the activity of PKC genes and the signatures of various immune cell subpopulations, we reported that in most cancer types, the levels of PRKCB, PRKCH, and PRKCQ were positively associated with the infiltration of most immune cells." (PMID 35174160, 2021). "We found that PRKCB, PRKCH, and PRKCQ levels were directly associated with HLAs scores in almost most cancers, especially for PRKCB, whose elevated expression moderately to strongly controlled the HLA level in 28 cancer types (R ˃ 0.3)." (PMID 35174160, 2021). "PRKCQ is expressed in a subset of GIST cancers and regulates their proliferation." (PMID 32600444, 2020). "PRKCQ is a novel PKC family member, preferentially expressed in the TNBC subtype and drives growth factor-independent growth, anoikis resistance, migration, and EMT, all properties associated with tumorigenesis and metastatic spread of cancer cells." (PMID 32600444, 2020). "Overexpression of PRKCQ and AKT3 are associated with invasive cancer phenotypes." (PMID 22546513, 2012). "Collectively, the expression levels of PRKCI and PRKCG were elevated in most of the significantly compared cancers, while PRKCA, PRKCB, PRKCE, and PRKCQ tended to be downregulated among most cancer types." (PMID 35174160, 2021). "The most crucial finding in this study was that PKC isoenzymes are robust biomarkers for the tumor immune status, PRKCB, PRKCH, and PRKCQ as stimulators, while PRKCI and PRKCZ as inhibitors in most cancers." (PMID 35174160, 2021). "In contrast, the function of PRKCQ in non-hematopoietic tissues and cancers remains to be fully elucidated." (PMID 32600444, 2020). "In contrast, the functions of PRKCQ in non-hematopoietic tissue and in cancer have not yet been fully elucidated." (PMID 27663795, 2016).
tumor (15 papers, 2016 to 2025). "The identification of PRKCQ as a protective factor suggests its potential as a therapeutic target, particularly in strategies aimed at enhancing anti‐tumor immunity." (PMID 40817807, 2025). "By inducing insulin resistance phenotype, activated PRKCQ limited the access of tumor cells to glucose." (PMID 36118894, 2022). "Our data further support the promising potential of PRKCQ inhibition as a therapeutic strategy to suppress TNBC tumor growth and survival in combination with standard-of-care chemotherapy." (PMID 32600444, 2020). "Consistent with the phenotypes observed in the in vitro cultures, PRKCQ/PKCθ downregulation impaired growth of triple-negative breast primary tumor xenografts." (PMID 27663795, 2016). "Collectively, these data demonstrate that overexpression and activation of PKCθ caused by PRKCQ amplification resulted in oncogenic activation of the TCR signaling pathway in the patient, setting the stage for the tumor-suppressive effect of PD-1 signaling in malignant T cells." (PMID 36649072, 2023). "Furthermore, PRKCQ stimulates tumor immune recognition by inducing T cell receptor (TCR) pathways and inhibiting Treg cells." (PMID 35174160, 2021). "The use of these isoform-specific PRKCQ inhibitors could provide unique insights into the interaction between triple-negative tumor cells, their immune microenvironment and systemic immune responses." (PMID 27663795, 2016). "The model includes PRKCQ, FUOM, H2BC21, LAMTOR4, and HCG22, along with critical clinical factors such as age, tumor grade, and tumor stage (T and N)." (PMID 40817807, 2025). "Related to the proliferation and function of immune cells or tumor progression, T cell proliferation-related genes (TRGs) involve hundreds of protein-coding genes which include CTLA4, HHLA2, PRKCQ, IL4I1, IL20RB, HOMER1, DHPS, and so on." (PMID 36118894, 2022). "Expression of LSD1, a downstream substrate of PRKCQ and driver of EMT, was reported to be enriched among chemotherapy-resistant triple-negative xenograft tumors and patient circulating tumor cells." (PMID 32600444, 2020). "Key findings include the identification of FUOM, PRKCQ, H2BC21, and LAMTOR4 as pivotal regulators of tumor progression and immune modulation, with FUOM playing a particularly prominent role in promoting cell proliferation, migration, and colony formation, as demonstrated by experimental validation." (PMID 40817807, 2025). "Moreover, LYN, MMP2, PRKCQ, and TLR1 can affect SKCM by influencing tumor cell metastasis, UV-induced cell injury, the NF-κB signaling pathway, and apoptosis." (PMID 36171883, 2022).
infection (1 paper, 2026). The state of being infected such as from the introduction of a foreign agent such as serum, vaccine, antigenic substance or organism. "In contrast, PRKCQ expression was markedly downregulated in the infection group.The raw Ct values for the qPCR validation experiments are provided in S8 Table.These orthogonal validation results corroborate the relevance of the identified DE-PCDs in S. aureus pneumonia pathogenesis." (PMID 41557688, 2026).
PRKCQ also shares sentences with these, for which no sentence is quoted: gastrointestinal stromal tumor (3 papers); ovarian carcinoma (2); T-cell leukemia (2); thyroid cancer (2); age (1); allergic disease (1); Arthritis (1); atherosclerosis (1); Behcet disease (1); colorectal cancer (1); COVID-19 (1); dilated cardiomyopathy (1); eczema (1); hay fever (1); Hypertension (1); infectious disease (1); leukemia (1); multiple sclerosis (1); Neurological Disease (1); renal cell carcinoma (1); septic shock (1); T-cell lymphoma (1); type 2 diabetes (1); uveal melanoma (1).